Y_RNA (Y RNA )
Gene: Miscellaneous RNA gene on chromosome 2 (135,810,169 to 135,810,279, reverse strand). Ensembl gene ENSG00000200664.
Homologues: Orthologues: chimpanzee Y_RNA (98% identical). Paralogues in human: RNY1 (84% identical), Y_RNA (82% identical), Y_RNA (81% identical), Y_RNA (80% identical), Y_RNA (79% identical), RNY1P11 (78% identical), Y_RNA (78% identical), Y_RNA (77% identical), RNY1P12 (77% identical), RNY1P5 (77% identical), RNY1P7 (77% identical), RNY1P10 (76% identical), and 92 more.